DCC (DCC netrin 1 receptor)
Diseases named in the same sentence as DCC in open-access papers (continued):
Sharing a sentence is not in itself a finding about the gene and the disease.
Anxiety (1 paper, 2022). Intense feelings of nervousness, tension, or panic often arise in response to interpersonal stresses. "Altogether, a novel hypothesis emerged that the activation of the Netrin-1/DCC/GluA1 pathway, which resulted in strengthening hippocampal LTP in MS rats, finally led to the visceral hypersensitivity and anxiety-like behaviors from the post-weaning period to adulthood." (PMID 35966013, 2022).
anxiety disorder (1 paper, 2022). A category of psychiatric disorders which are characterized by anxious feelings or fear often accompanied by physical symptoms associated with anxiety. "Moreover, the results suggested that Netrin-1/DCC/GluA1 signaling pathway may be a potential therapeutic target for the treatment of visceral hypersensitivity and associated anxiety disorder." (PMID 35966013, 2022). "These novel findings suggest that long-lasting over-expression of Netrin-1 can mediate visceral hypersensitivity and anxiety disorder from the post-weaning period to adulthood by activating DCC/GluA1 pathway in the hippocampus." (PMID 35966013, 2022). "Using a combination of RNA-Seq, behavioral tests, lentivirus interference, and molecular biology techniques, we found that over-expression of Netrin-1 could induce visceral hypersensitivity and anxiety disorder in different life periods through activating DCC/GluA1 pathway in the hippocampus." (PMID 35966013, 2022).
apoptosis (1 paper, 2024). "When the DCC gene is mutated, netrin-1 (ligand produced in the crypts of the colorectal mucosa) does not bind to the DCC transmembrane protein, resulting in abnormal cell survival (apoptosis disorders)." (PMID 38396715, 2024).
astrocytic tumor (1 paper, 2018). A glial tumor of the brain or spinal cord showing astrocytic differentiation. "Downregulation of DCC expression was suggested as an important marker in tumor malignancy and recurrence in astrocytic tumors." (PMID 29805753, 2018).
autism spectrum disorder (1 paper, 2023). A spectrum of developmental disorders that includes autism, and Asperger syndrome. "Pathogenic variants of DCC, Robo, and other guidance cue receptors are also associated with autism spectrum disorders [ASDs; as reviewed in Bedogni and Hevner (2021)]." (PMID 37941606, 2023).
bone cancer (1 paper, 2025). A primary or metastatic malignant neoplasm affecting the bone or articular cartilage. "In adult disease models, aberrant netrin-1: DCC signaling drives pathological nerve sprouting and pain: for example, in a rat bone cancer pain model, tumor-derived netrin-1 activates DCC to promote nociceptive neuron sprouting, and DCC inhibition attenuates hyperalgesia." (PMID 40728980, 2025).
carpal tunnel syndrome (1 paper, 2026). Entrapment of the median nerve in the wrist that is characterized by numbness, tingling and painful movement. "These included associations with genes involved in neurotransmitter signaling (HTR3A), immune function (HLA-DQB1, BCL11A), extracellular matrix remodeling (COL11A1, ADAMTS17, LOXL4), axon guidance and neural development (DCC, ETV1, NEGR1), and carpal tunnel syndrome (DIRC3)." (PMID 41518141, 2026).
childhood asthma (1 paper, 2020). "The novel loci included SNPs in or near the DENND1B (DENN domain containing 1B) gene, which has been implicated in childhood asthma; RNF103 (ring finger protein 103), a suspected antidepressant target and genes related to axon guidance (DCC netrin 1 receptor)." (PMID 31576797, 2020).
chronic neutrophilic leukemia (1 paper, 2022). A rare chronic myeloproliferative neoplasm characterized by neutrophilic leukocytosis. "In another study on a rare form of MPN; that is, chronic neutrophilic leukemia, the role of DCC was investigated in the MPN subcategories." (PMID 35176183, 2022).
Coffin-Siris syndrome (1 paper, 2021). Coffin-Siris syndrome (CSS) is a rare congenital multi-systemic genetic disorder characterized by aplasia or hypoplasia of the distal phalanx or nail of the fifth digit, developmental delay, intellectual disability, coarse facial features, and other variable clinical manifestations. "Mutations were detected in four of them: one with a mutation in the ARID1B gene (Coffin–Siris syndrome), one with a microdeletion (Xq28), one with a non‐relevant heterozygous mutation in the DISP1 gene and one with a DCC mutation." (PMID 32484578, 2021).
cognitive deficits (1 paper, 2023). "Here we show that amphetamine, by dysregulating Netrin-1/DCC signaling, triggers ectopic growth of mesolimbic dopamine axons to the prefrontal cortex, only in early-adolescent male mice, underlying a male-specific vulnerability to enduring cognitive deficits." (PMID 37419977, 2023).
colitis (1 paper, 2021). Inflammation of the colon. "Using scRNASeq, we are able to confirm IFNG production in T cells that overlap with the TRM cell zones and that IFNG production is detected in all UC, DCC, and anti–PD-1 colitis (PDC) groups." (PMID 34147519, 2021).
congenital mirror movement disorder (1 paper, 2021). "Mutations in the DCC gene have been found in those with congenital mirror movement disorder (MRMV-1; and it has also been previously associated with a range of complex brain-related traits, including suicidality, mood instability, intelligence and putamen volume." (PMID 33830993, 2021).
diabetes (1 paper, 2017). "Surprisingly, diabetes also markedly increased DCC mRNA and protein expression in aortas of WT mice compared those of non-diabetic WT mice." (PMID 29059224, 2017).
diabetic kidney disease (1 paper, 2021). Progressive kidney disorder caused by vascular damage to the glomerular capillaries, in patients with diabetes mellitus. "Recent investigations demonstrated that DCC (DCC netrin 1 receptor) gene can mediate angiogenesis and plays an important role in diabetic kidney disease." (PMID 33827531, 2021).
follicular lymphoma (1 paper, 2012). Follicular lymphoma is a form of non-Hodgkin lymphoma characterized by a proliferation of B cells whose nodular structure of follicular architecture is preserved. "For example, ID4 has been shown to act as a putative tumour suppressor gene in AML, DCC is hypermethylated in follicular lymphoma and mutation of TERT increases the risk of familial AML." (PMID 22479372, 2012).
heart failure (1 paper, 2022). Inability of the heart to pump blood at an adequate rate to meet tissue metabolic requirements. "The lncRNA CHRF derived from the intron of the DCC (DCC netrin 1 receptor) gene has been shown to be upregulated in DOX-induced heart failure, both in vitro, and in vivo." (PMID 35246252, 2022).
hematoma (1 paper, 2017). A hematoma is a collection of blood from a vascular structure into an extravascular space. "Immunofluorescence staining of DCC and UNC5H2 was also performed to assess further the upregulated protein levels in neurons in the peri-hematoma cortex." (PMID 29375318, 2017). "Twenty-four hours after ICH, both DCC and UNC5H2 were upregulated in the peri-hematoma cortex, and DCC was elevated more significantly." (PMID 29375318, 2017).
heroin addiction (1 paper, 2016). "Our study provides direct evidence that polymorphisms of the DCC gene are associated with heroin addiction in the Chinese Han population." (PMID 27676367, 2016). "DCC may be an important candidate gene in heroin addiction, and rs16956878, rs12607853, and rs2292043 may be risk factors, thereby providing a basis for further genetic and biological research." (PMID 27676367, 2016).
hypopharyngeal cancer (1 paper, 2024). Carcinoma, predominantly squamous cell, arising from the epithelial cells of the hypopharynx. "In this study, methylation values of the DNA promoter region of the DCC gene in saliva samples showed high diagnostic accuracy for hypopharyngeal cancer, with a sensitivity of 83.6% and a specificity of 90.2%, even at the superficial cancer stage." (PMID 38538728, 2024). "In this study, we determined that the DNA promoter region of DCC in saliva was hypermethylated in more than 80% of patients with superficial hypopharyngeal cancer and could be used as a reliable diagnostic marker." (PMID 38538728, 2024). "In 12 patients with hypopharyngeal cancer, for which post-treatment saliva samples have been collected to date, we compared the methylation values of the DCC gene in saliva samples before and after cancer resection." (PMID 38538728, 2024). "Therefore, we conclude that aberrant methylation of DCC in the saliva of patients with superficial hypopharyngeal cancer is a reliable, disease-specific factor." (PMID 38538728, 2024).
mammary adenocarcinoma (1 paper, 2017). "The reports of serine protease depletion of DCC included the observation that the soybean BBI blocked the ability of chymotrypsin to down-regulate DCC and also blocked the increased migration of MCF-7 human breast adenocarcinoma cells produced by chymotrypsin." (PMID 28238104, 2017).
metabolic syndrome (1 paper, 2022). A cluster of metabolic risk factors for CARDIOVASCULAR DISEASES and TYPE 2 DIABETES MELLITUS. "In the metabolic syndrome sub-network, five genes had high degrees of connection and could be considered hub genes: PTPRD, DCC Netrin 1 Receptor (DCC), Proprotein Convertase Subtilisin/kexin Type 6 (PCSK6), Unc-13 Homolog C (UNC13C), and Contactin 4 (CNTN4)." (PMID 35121771, 2022).
mucinous carcinoma (1 paper, 2016). "A previous study found increased DCC expression but a lower rate of axillary lymph node metastasis in mucinous carcinoma than in non-mucinous carcinoma in the human female breast." (PMID 27127179, 2016).
myocardial infarction (1 paper, 2017). Gross necrosis of the myocardium, as a result of interruption of the blood supply to the area, as in coronary thrombosis. "In the model of ischemia/reperfusion-induced myocardial infarction, with Netrin-1 treatment, Netrin-1 receptors were detected, in which the mRNA and protein level of DCC were abundantly elevated, which is consistent with our research." (PMID 29321724, 2017).
osteosarcoma (1 paper, 1997). A usually aggressive malignant bone-forming mesenchymal neoplasm, predominantly affecting adolescents and young adults. "In human osteosarcoma allelic loss frequently occurs on the long arm of chromosome 18, suggesting a possible involvement of the DCC gene in the pathogenesis of this tumour entity." (PMID 9155051, 1997). "In view of the putative tumour-suppressor characteristics of the DCC gene its loss or reduction of expression could be a specific event in the development or progression of many high-grade osteosarcomas." (PMID 9155051, 1997).
polyneuropathy (1 paper, 2021). A disease or disorder affecting more than one nerve. "In skin samples of patients with polyneuropathy, NTN1 in proximal and DCC and NEO1 (two attracting receptors) in distal specimens are reduced." (PMID 34576252, 2021).
psoriasis (1 paper, 2022). An autoimmune condition characterized by red, well-delineated plaques with silvery scales that are usually on the extensor surfaces and scalp. "Through comprehensive bioinformatic analysis, this study identified DEGs normal in psoriasis; that is, gathering in DNA replication, cell cycle, DCC-intervened pathways, and Netrin-1 flagging pathways." (PMID 36499614, 2022).
psychosis (1 paper, 2020). "In the following sections, we collate the evidence that similar DCC and Netrin-1 related effects occur in humans, influencing susceptibility to mood disorders, psychosis, and addictions." (PMID 31659271, 2020). "Most recently, by applying next-generation sequencing, which sequences the entire genome and can detect rare variants, loci in five genes, including DCC, were shared among three family members exhibiting atypical psychosis." (PMID 31659271, 2020).
radiculopathy (1 paper, 2021). Disease involving a spinal nerve root (see spinal nerve roots) which may result from compression related to intervertebral disk displacement; spinal cord injuries; spinal diseases; and other conditions. "Thus, we aimed to examine if LBP with radiculopathy 12 months after an acute episode of radiculopathy is associated with the selected SNPs; SOX5 rs34616559, CCDC26/GSDMC rs7833174 and DCC rs4384683." (PMID 35140737, 2021). "Thus, we examine if LBP with radiculopathy 12 months after an acute episode of LBP with radiculopathy is associated with the selected single nucleotide polymorphisms (SNPs); SOX5 rs34616559, CCDC26/GSDMC rs7833174 and DCC rs4384683." (PMID 35140737, 2021). "Our data did not support the hypothesis that LBP with radiculopathy 12 months after an acute episode of LBP with radiculopathy is associated with the selected SNPs; SOX5 rs34616559, CCDC26/GSDMC rs7833174 and DCC rs4384683." (PMID 35140737, 2021).
scoliosis (1 paper, 2021). A congenital or acquired spinal deformity characterized by lateral curvature of the spine. "Mutations in DCC have been shown to result in disruption of the midline-bridging neuronal commissures of the brain, causing horizontal gaze palsy, scoliosis and intellectual disability." (PMID 33795730, 2021).
soft-tissue tumours (1 paper, 1994). "We have also examined the role of the DCC tumour-suppressor gene in the development of human soft-tissue tumours in a variety of histological types." (PMID 8198970, 1994).
transient cerebral ischemia (1 paper, 2018). "Furthermore, DCC is expressed in both neurons and astrocytic feet and affects the promoting effects of Netrin-1 on axonal growth after a transient cerebral ischemia." (PMID 29487502, 2018).
viral infection (1 paper, 2025). "The expression of Netrin-1 and DCC proteins was significantly lower in the Netrin-1 and DCC co-overexpression control group compared to that in the Netrin-1 and DCC co-low-expression control group, indicating successful viral infection." (PMID 40092657, 2025).
tumor (144 papers, 1994 to 2025). "The role of Netrin-1 is context-dependent: it fosters tumor progression in chronic inflammation through DCC pathway upregulation but has also been implicated in glioma cell motility inhibition." (PMID 40243726, 2025). "The nucleoside diphosphate kinase 1 (NME1) and netrin 1 receptor (DCC) genes have been associated with resistance against tumorigenesis and tumor metastasis." (PMID 38556604, 2024). "DCC is a putative tumor suppressor gene located at 18q21 that encodes a transmembrane protein involved in both epithelial and neuronal cell differentiation." (PMID 38538728, 2024). "DCC encodes for a nectrin-1 receptor and functions as a tumor suppressor gene with apoptotic ability, while SMAD4 regulates the TGF-β pathway to limit tumor growth and invasion." (PMID 35565354, 2022). "Neogenin, also known as a tumor suppressor protein Deleted in Colorectal Cancer (DCC), is low-expressed in many cancers, and this deficiency of neogenin increases the risk of tumor malignancy." (PMID 32318624, 2020). "Further, the known tumor suppressors DCC and GPRC5A were underexpressed with underlying reduced copy number." (PMID 31682594, 2019). "DCC has been strongly linked to caspase activity, and DCC acts as a tumor suppressor via its dependence receptor activity." (PMID 30340315, 2018). "The DCC caspase cleavage site is required to trigger apoptosis, and mutation of the site in mice prevents tumor suppression." (PMID 30340315, 2018). "The SNP, AX-104130346, occurs in an intron of the DCC gene, a gene whose corresponding protein has been associated with apoptosis and functions as a tumor suppressor." (PMID 27070818, 2016). "Three homozygous variants were present in the tumour suppressor DCC (Deleted in Colorectal Carcinoma), which encodes a netrin receptor required for cell differentiation, and also the induction of apoptosis in the absence of ligand." (PMID 21750719, 2011). "Deleted in colorectal cancer protein (DCC) has been proposed as a putative tumour suppressor, and loss of DCC expression has been associated with poor prognosis and risk of metastasis." (PMID 21339979, 2010). "Among the 294 tumours for which gene dosage data (Smad2, Smad4 and DCC) were available, 167 tumours (57%) showed heterozygous loss of Smad4, and 73 out of 167 samples were randomly chosen for mutation analysis." (PMID 12569386, 2003). "Methylated status of DCC was significantly correlated with the loss of DCC expression in primary tumours (P< 0.01)." (PMID 11461076, 2001). "The 'deleted in colon carcinoma' (DCC) gene has been considered a candidate tumour-suppressor gene that encodes for a transmembrane protein with strong structural similarity to members of the superfamily of neural cell adhesion molecules." (PMID 9155051, 1997). "The DCC (Deleted in Colorectal Carcinoma) gene is located on the long arm of chromosome 18 and encodes the transmembrane protein DCC which is called the “conditional tumor suppressor gene”." (PMID 38396715, 2024). "Indeed, the inactivation of UNC5C, and DCC, or the mutation of the DCC‐inducing apoptosis domain is associated with tumor development and progression in mouse models." (PMID 27378792, 2016). "In addition, it appears that RAC1P29S frequently associates with the netrin 1 receptor, DCC, a tumor suppressor which can mediate signals that promote proliferation and migration." (PMID 23372575, 2012). "This modulation underscores the pivotal role of DCC-2036 in reshaping the immune landscape within the tumor, suggesting its potential to boost the efficacy of immunotherapeutic strategies in CRC." (PMID 39788945, 2025). "Further studies indicated that the impact of DCC-2036 on CRC extends beyond direct tumor cell inhibition, as it profoundly influences the immune microenvironment." (PMID 39788945, 2025).